STAT4 (signal transducer and activator of transcription 4)
Diseases named in the same sentence as STAT4 in open-access papers (continued):
Sharing a sentence is not in itself a finding about the gene and the disease.
infection (continued). "The rapidity of the response observed during infections suggested that STAT4 function in innate immune cells was required for this response, but specific subpopulations of STAT4-dependent innate immune cells that are responsible for the phenotype have not been identified." (PMID 34138758, 2021). "However, STAT4 protein levels were the same in all three infection conditions (WT, ΔYopB, and YopJC172AY. pseudotuberculosis)." (PMID 34871329, 2021). "In models of infection and autoimmunity, STAT4 is a critical component in developing inflammation." (PMID 34138758, 2021). "Thus, STAT4-dependent susceptibility to MRSA and inability to clear infection are likely due to defective neutrophil functions in the PC (ROS production, NETosis, bacterial killing) but not due to defective trafficking of neutrophils to the site of infection." (PMID 34138758, 2021). "We could, for example, verify that expression of IL10 or SOCS3 genes is reduced during the infection or that expression of STAT4, LAMP3, ADORA2A and BIRC3 genes peaks 6 h pi." (PMID 32070192, 2020). "For example, although Leishmania major evokes an IL-4 response in IL-12p40 KO mice, the diminished Th1 response observed in STAT4-deficient mice following infection with L. major or Toxoplasma gondii was not accompanied by a compensatory Th2 response." (PMID 18990205, 2008). "Early studies also demonstrated that Th1 cytokines are associated with IgG2a Ab production, whereas STAT4 deficiency is associated with a reduction in IFN-γ production, increases in Th2-associated cytokines, and a switch to IgG1 Ab production in immunization and infection systems." (PMID 33446493, 2021). "Indeed, STAT4-deficient ILC1-like cells were diminished following infection, while chimerism of NK cells and ILC1s remained equal between uninfected and infected chimeric mice, suggesting that T. gondii-induced ILC1-like cells were dependent on STAT4." (PMID 31393266, 2019). "However, IL13RA, IL3RA, IL4, STAT1, STAT4 were down-regulated at this time point of infection." (PMID 21439068, 2011). "The number of activated T cells (subset 2) increased substantially after infection with upregulation of the IFNG, STAT3, STAT4, IL9, FOXP3, and TGFBR1, TGFBR2 genes." (PMID 40573402, 2025). "Western blot analysis indicated the presence of elevated phosphorylated-STAT4 (pSTAT4) and phosphorylated-STAT1 (pSTAT1) levels at 8, 12, and 24 hours post-infection." (PMID 39119293, 2024). "STAT4 is indispensable for the induction of TH1 immune responses, while STAT3 is critical for the TH17 response against recurrent infections and establishment of T cell memory subsets." (PMID 36916966, 2023). "Apart from this, certain studies have ascertained the critical role of STAT4 in regulating TRM differentiation and persistence in achieving tissue-specific immunity against infections." (PMID 36881595, 2023). "Significant differences (p < 0.05) in the expression of only STAT1, STAT4, TRAF6, and NFKB1 factors were observed for the different types of macrophages, at different times of infection." (PMID 35774406, 2022). "STAT1−/− and STAT4−/− mice infected with LmexWT showed significant footpad swelling starting at 2 weeks post-infection (wpi) for STAT1−/−, and at 3 wpi for STAT4−/−." (PMID 35236861, 2022). "Out of the four Jak-STAT signaling molecules (suppressor of cytokine signaling 1 [SOCS1], SOCS3, STAT1, and STAT4) analyzed in this study, only the STAT1 gene was significantly upregulated (36 to 48 hpi) in ALI-PRECs following infection with PHEV." (PMID 34935443, 2021). "The impaired ability of hybrid Th1/Tfh to help antibody production is likely due to an antagonism regulating Tfh effector functions through the network of STAT4 and T-bet expression and the effects of IL-2, IL-12, IFN-γ, and/or TNF, depending on the infection." (PMID 32634740, 2020).
infection (continued). "Here, we show that the transcription factor STAT4 regulated the expression of ST2 on CTLs in vitro and in vivo in primary infections with lymphocytic choriomeningitis virus (LCMV)." (PMID 31447845, 2019). "Higher basal levels of STAT-4 in healthy and BT/TT individuals in our study correlated with significant Th1 response in these individuals and may be responsible for their protective immunity which ultimately prevents the infection in healthy and restricts the same in BT/TT patients." (PMID 30642265, 2019). "The importance of balanced cellular STAT levels has been shown for infection with Lymphocytic Choriomenengitis Virus (LCMV): the ratios of basal and induced STAT1/STAT4 determine the innate and adaptive immune cell activities." (PMID 24489749, 2014). "In support of this hypothesis, our results show that activation of the CGRP receptor by CGRP and SAX results in an increased expression of langerin and STAT4, which are involved in the inhibition of HIV-1 trans-infection." (PMID 34956215, 2021). "Of the 14 Th1 response genes tested, the expression levels of 8 genes (IL2, IFNG, CSF2, TLR4, CD4, IRF1, SOCS5 and STAT4) were significantly elevated at 2 weeks and several of these (IL2, IFNG, TLR4, CD4 and STAT4) had similar expression levels at 4 and 8 weeks post-infection." (PMID 23448601, 2013). "ILC1s produce optimal IFN-γ in a signal transducer and activator of transcription 4 (STAT4)-dependent manner via tissue-resident X-C motif chemokine receptor 1-positive conventional dendritic cells (XCR1+ cDC1), thereby limiting viral replication at the initial site of infection." (PMID 37908364, 2023). "Thus, we compared the activation of STAT-4 after 2-h infection with or without IL-12 stimulation in NK92 cell line." (PMID 29067027, 2017). "Interestingly, at 24 h post infection there was no further increase in immune responsive genes but down-regulation of STAT4, TNFR, IL4R, and TNF6 genes were found." (PMID 21439068, 2011). "However, the exact role of STAT4 in the regulation of foreign Ag–driven AFC and GC responses during immunization or infection is not clear." (PMID 33446493, 2021). "Mechanistically, T-bet, and not STAT1 or STAT4, regulated IFN-γ production by T cells; and T cell-intrinsic expression of STAT3, Bcl6, and Blimp-1 each regulated T-bet expression during the peak of infection." (PMID 32634740, 2020).
kidney disease (5 papers, 2008 to 2023). "From these, the most significant associations have been detected between renal disorder and genetic variation in the ITGAM and STAT4 genes, which have been also associated with discoid rash and oral ulceration, respectively." (PMID 28619073, 2017). "Accumulated evidence have suggested that STAT4 are involved in the pathogenesis of renal disorders." (PMID 29467950, 2018). "Conversely, the reported association between renal disorder and ITGAM and STAT4 genes was not replicated." (PMID 28619073, 2017).
adenocarcinoma (3 papers, 2020 to 2023). A common cancer characterized by the presence of malignant glandular cells. "The regulatory relationship between PCNP and STAT3/STAT4 has not been previously reported, although upregulated STAT3 and STAT5 were detected in adenocarcinoma cells overexpressing PCNP, and were found accountable for enhanced cell proliferative, migrated, and invasive abilities." (PMID 35468892, 2022).
bacterial infection (3 papers, 2018 to 2021). "Our finding is also of high interest as these data provide evidence for a critical role of STAT4 for neutrophil-dependent immunity against bacterial infections." (PMID 34138758, 2021). "Many of the highly expressed genes encode important factors of the innate immunity such as IL-1A, IL-6, IL-23A, TNF superfamily proteins, CCL and CXCL chemokine families and NFκB and STAT4 regulators and belong to common expression pattern mounted by host cells upon bacterial infection." (PMID 32070192, 2020).
cardiovascular diseases (2 papers, 2017 to 2024). "This evidence implicates a genetic predisposition via STAT4 to some cardiovascular diseases." (PMID 28256502, 2017). "Several studies have provided clues that the Stat4-mediated inflammation is involved in cardiovascular diseases." (PMID 28256502, 2017).
gastrointestinal tumor (1 paper, 2024). "We further found NOTCH3 levels in gastrointestinal tumor to correlate with markers of Dendritic cell(HLA-DPB1, HLA-DRA, HLA-DPA1, BDCA-4), Tfh(T-bet, STAT4, STAT1, TNF-α), Treg cells (FOXP3, CCR8, STAT5B, TGFβ) and T cell exhaustion (PD-1, CTLA4, LAG3, TIM-3)." (PMID 38906903, 2024).
inflammation (1 paper, 2024). Aberrant reaction of the microcirculation characterized by movement of fluid and leukocytes from the blood into extravascular tissues. "IL-12 induces TH1 cell differentiation by activation and phosphorylation of the signal transducer and activator of transcription 4 (STAT4), and drives TH1-mediated intestinal inflammation." (PMID 38395946, 2024).
neurodegenerative disease (1 paper, 2023). A disorder of the central nervous system characterized by gradual and progressive loss of neural tissue and neurologic function. "It remains to be determined what effect selectively targeting Stat4 in myeloid cells, neurons or glia may have on declines in long-term, activity-dependent synaptic plasticity and cognition in normal aging or neurodegenerative diseases." (PMID 37783748, 2023). "However, our data suggests that suppression of inflammation by targeting Stat4, in both immune cells and neurons, may be a method for preventing, or even reversing, the loss of LTP observed in AD and other neurodegenerative diseases associated with impairments in cognitive function." (PMID 37783748, 2023).
vasculopathy (1 paper, 2012). "Vasculopathy in STAT4-deficient mice, which are nonresponders to IL-12 stimulation and are incapable of generating Th1 responses, is less intense than the vasculopathy observed in wild-type mice." (PMID 22720132, 2012).
STAT4 also shares sentences with these, for which no sentence is quoted: primary biliary cholangitis (4 papers); cognitive decline (3); glomerulonephritis (3); bladder (2); gastric adenocarcinoma (2); glioblastoma (2); Hashimoto thyroiditis (2); ischaemic stroke (2); pancreatic adenocarcinoma (2); renal failure (2); schizophrenia (2); -dependent (1); abdominal aortic aneurysm (1); allergic disease (1); alopecia (1); Alopecia universalis (1); Alzheimer disease (1); angioimmunoblastic T-cell lymphoma (1); ankylosing spondylitis (1); Aortic dissection (1); Autoimmune Addison's Disease (1); autoimmune cardiomyopathy (1); autoimmune uveitis (1); bladder tumor (1); brain tumors (1); breast invasive carcinoma (1); bullous pemphigoid (1); cervical adenocarcinoma (1); chronic cervicitis (1); chronic lymphocytic leukemia (1).
A further 52 diseases each share a sentence with STAT4 in 1 paper.